TSLP (thymic stromal lymphopoietin)
Diseases named in the same sentence as TSLP in open-access papers (continued):
Sharing a sentence is not in itself a finding about the gene and the disease.
atopic dermatitis (continued). "The expression of TSLP and IL33 is increased in the skin of human patients with atopic dermatitis." (PMID 32687504, 2020). "In addition, epidermal keratinocytes of atopic dermatitis patients are also able to produce LPGDS-derived PGD2, whereby the PGD2-metabolite 15d-PGJ2 seems to attenuate TSLP production of keratinocytes." (PMID 31226822, 2019). "Another group utilized a mouse model of TSLP-driven atopic dermatitis and demonstrated that ILC2 activation occurs independent of IL-33, but is dependent on TSLP receptor signaling." (PMID 24876829, 2013). "However, it is crucial to emphasize that no significant changes were observed in classic factors of atopic dermatitis, such as TSLP and pro-inflammatory cytokines (TNF-α, COX-2, IL-6, IL-31, etc.), in our study." (PMID 38834629, 2024). "Besides, promoter demethylation is found to contribute to the TSLP overexpression in skin lesion of patients with atopic dermatitis (AD), and treating keratinocytes with demethylating agent AZA reduces the methylation of TSLP promoter and increases TSLP transcription." (PMID 33652749, 2021). "Besides the antimicrobial effect, we have recently disclosed the curative effect of OSO against atopic dermatitis (AD) in the mouse model, where we observed that the topical application of OSO significantly affected the infiltration of mast cells, filaggrin, and thymic stromal lymphopoietin (TSLP)." (PMID 38790634, 2024). "Similarly, mice overexpressing TSLP but lacking T cells also develop atopic dermatitis." (PMID 23472158, 2013).
dermatitis (76 papers, 2010 to 2025). An inflammatory process affecting the skin. "The uncontrolled TSLP signaling plays a key role in patients with Netherton Syndrome, a rare hereditary skin disorder manifested by a susceptibility to AD, scaling skin, and hair abnormalities." (PMID 36344555, 2022). "Dermatitis is typically associated with both skin-produced cytokines (e.g., IL-33, -17C, and TSLP), and a skewing of CD4+ T cells into T helper 2 (Th2) and their associated cytokines (e.g., IL-4,-5,-13,)." (PMID 33017398, 2020). "IL-25 and IL-33 are overexpressed in skin of patients with AD,16, 49, 50, 51 with TSLP overexpression associated with skin inflammation in mice." (PMID 26299987, 2016). "Furthermore, our study suggests that I3C mitigates AD-related skin inflammation by downregulating TSLP/periostin expression and inhibiting the signaling pathways associated with TSLP/periostin, including NF-κB and MAPK." (PMID 39722037, 2024). "Thus, epidermal keratinocyte-specific STAT3 deficiency can aggravate AD-like skin inflammation in mice, possibly through TSLP dysregulation." (PMID 38053996, 2023). "FC alleviated AD apparent symptoms, such as dermatitis score, transepidermal water loss, epidermal thickness, and mast cell infiltration upon declining pro-inflammatory cytokines and mediators, IL-6, IL-5, IL-13, TSLP, and TNF-α." (PMID 37689763, 2023). "Besides, numerous investigations in both human and mouse skin implicated TSLP in a great variety of cutaneous disorders beyond AD." (PMID 34249003, 2021). "In addition, we observed that the altered gut microbiota can be the prognostic factors to predict the pathogenesis of AD: the abundance of Alistipes was positively associated with the expressions of TSLP in the skin, suggesting a close influence of gut microbiota on skin inflammation." (PMID 38473999, 2024). "Since TSLP receptors are expressed in various immune cells, including ILC2s, the TSLP-TSLP receptor interaction activates ILC2s to produce type 2 cytokines, such as IL-4, IL-5, and IL-13 and stimulates eosinophils, basophils, and dendritic cells, which eventually causes AD-like skin inflammation." (PMID 36983043, 2023). "β-Caryophyllene (BCP)—a selective CB2 agonist—ameliorates DNCB-induced AD-like dermatitis and downregulates keratinocyte TSLP/EGR1, supporting antipruritic and anti-inflammatory actions consistent with our cytokine trends." (PMID 41471858, 2025). "The administration of these bacteria has improved dermatitis score, and scratching behavior, and decreased the levels of IgE and TSLP in vivo." (PMID 38342758, 2024). "In light of this, our study sought to investigate the therapeutic potential of targeting periostin and TSLP in AD-like skin inflammation." (PMID 39722037, 2024). "In mouse models of AD, topical application of MC903 induces TSLP expression in epidermal keratinocytes, triggering AD-like dermatitis." (PMID 38590314, 2024). "Our investigation reveals the collaborative involvement of the MAPK/NF-κB and AhR pathways in DNCB-induced AD-like skin inflammation and barrier dysfunction orchestrated by TSLP and periostin, effects substantially mitigated by I3C treatment." (PMID 39722037, 2024). "In relevant studies on the pathogenesis of AD, the pathogenic role of keratinocyte derived cytokines such as thymic stromal lymphopoietin (TSLP), interleukin-33 (IL-33) and IL-25 in inducing skin inflammation has been emphasized." (PMID 38318507, 2023). "Dermatitis score was much lower in high-fat-fed NC-TSLP-KO mice, suggesting TSLP mediates a high-fat-diet-induced increase in dorsal skin inflammation." (PMID 37686715, 2023). "In AD, thymic stromal lymphopoietin (TSLP) is released from epithelial cells and is critical to the atopic march triggering skin inflammation." (PMID 38139833, 2023). "TSLP blockade attenuated DNCB-induced AD-like skin inflammation in Stat3 cKO mice, suggesting that keratinocyte-specific STAT3 dysfunction leads to TSLP-mediated skin inflammation in AD." (PMID 38053996, 2023).
dermatitis (continued). "Not only the expression of TSLP but also the skin inflammation was reduced significantly by DMOG treatment." (PMID 36983043, 2023). "We found that anti-TSLP antibody treatment attenuated DNCB-induced AD-like skin inflammation in Stat3 cKO mice, as the ear thickness and dermatitis score were significantly decreased." (PMID 38053996, 2023). "More importantly, blockade of TSLP activity by TSLP neutralizing antibody markedly reduced AD-like skin inflammation in Stat3 cKO mice." (PMID 38053996, 2023). "Several studies have reported that keratinocyte-derived cytokine TSLP acts as a master switch of AD skin inflammation." (PMID 38053996, 2023). "Epidermal barrier function largely relies on the SC barrier; perturbation of the SC barrier by tape stripping or acetone treatment has been shown to trigger the release of Th2 cytokines such as TSLP and IL-33, leading to subsequent skin inflammation." (PMID 35834333, 2022). "Mirroring murine models, human skin ILC2s can be activated by IL-25, IL-33, and TSLP, with high expression of IL-33 and TSLP during chronic skin inflammation." (PMID 35359972, 2022). "Mast cells were involved in TSLP production and induction of skin inflammation in MC903-induced dermatitis." (PMID 35874756, 2022). "In summary, this study provided evidence that the new infiltrated inflammatory Langerin+ DCs promoted the development of AD-like dermatitis by mediating the production of TSLP." (PMID 36304463, 2022). "MC903-induced dermatitis was dependent on thymic stromal lymphopoietin (TSLP), IL-25 and IL-33 in BALB/c mice, and on TSLP, but not IL-25 or IL-33, in C57BL/6 mice." (PMID 35874756, 2022). "Morphologically, TSLP was extensively expressed in the epidermis of each dermatosis, but the expression was weak in specimens of DLE." (PMID 36046760, 2022). "Studies have shown that TSLP is the initial stimulus of the skin inflammation and immune response that occur in keratinocytes." (PMID 34361003, 2021). "The results show that the administration of AES16-2M significantly reduced the dermatitis score, ear thickness, and the level of blood IgE and TSLP in AD mice." (PMID 33671791, 2021). "In the current study, we demonstrated that the short peptide AES16-2M, consisting of only five amino acids, attenuates AD symptoms, including dermatitis score, ear and epidermal layer thickness, sera IgE, and TSLP level in AD mice." (PMID 33671791, 2021). "Although innate immune responses play an important role in the MC903-induced AD-like dermatitis, in which TSLP and IL-33 produced by keratinocytes initiate the skin inflammation, adaptive immune cells are also required in the inflammation." (PMID 34868040, 2021). "High levels of TSLP can be found in blood and skin of AD patients, and transgenic overexpression in mice leads to spontaneous, AD-like dermatitis." (PMID 34833113, 2021). "TSLP from this mouse dermatitis model was also detectable in the serum of EGFR∆ep mice, with a peak expression around postnatal day 20, which represents two weeks after the start of the skin inflammation (p20)." (PMID 34833113, 2021). "TSLP expression is also observed in MC903-induced AD-like dermatitis mouse model, as it plays a crucial role in Th2-mediated inflammation." (PMID 33499346, 2021). "It was previously demonstrated that TSLP is highly produced by skin keratinocytes in dermatitis and psoriasis." (PMID 33029540, 2020). "Ruxolitinib cream ameliorated dermatitis symptoms by modulating the transcription of genes directly involved in TSLP signaling, such as IL-7 receptor (Il7r) and JAK-STATs." (PMID 33658996, 2020). "In contrast, overexpression of TSLP in keratinocytes triggered massive itching behavior together with the development of AD-like dermatitis." (PMID 31447854, 2019). "TSLP notably contributes to skin disorders like AD, and accordingly, binding to its specific receptor has been reported to regulate selected aspects of MC biology, including maturation and mediator secretion." (PMID 31387206, 2019).
dermatitis (continued). "Although it was at a low level, serum TSLP levels also significantly increased in DNFB-induced dermatitis of NC/Nga than in that of NC.h2b/b (p < 0.05, ANOVA)." (PMID 29416104, 2018). "The release of T helper 2 (Th2) cytokines, such as thymic stromal lymphopoietin (TSLP), interleukin (IL)-4, IL-5, IL-13, and IL-31, contributes to skin inflammation, pruritus, neuromodulation of peripheral nerves associated with pruritus transduction, and regulation of the skin barrier in AD." (PMID 40429704, 2025). "The promotion of IL-17A and IL-22 production induced by M. globosa may restrain the development of TSLP and inhibit the Th1/Th2 type skin inflammation." (PMID 40309262, 2025). "Similarly, thymic stromal lymphopoietin (TSLP), integral to type 2 immune responses, induces dermatitis in animal models and is elevated in human AD, yet clinical treatments like tezepelumab exhibit limited efficacy." (PMID 38590314, 2024). "Furthermore, the induction of AD-like dermatitis in TSLP transgenic mice underscores its significance, while the absence of TSLP receptors in mice leads to a failure in developing allergic skin inflammation following epicutaneous sensitization to allergens." (PMID 39722037, 2024). "In line with this theory, combined treatment with a PAR2 inhibitor and a lactobionic acid (LBA) (‘super acid’) exhibited therapeutic effects on hapten-induced atopic dermatitis (AD)-like dermatitis in a murine model in which elevations of epidermal TSLP paralleled development of the dermatitis." (PMID 37638035, 2023). "TSLP blockade significantly alleviated DNCB-induced AD-like skin inflammation in Stat3 cKO mice." (PMID 38053996, 2023). "Furthermore, TSLP promotes type 2 immune responses that have been reported to be the main mediator of inflammation in MC903-induced dermatitis model mice." (PMID 37298299, 2023). "Considering that ICB therapy commonly leads to immune adverse events like dermatitis, colitis, and pneumonitis, understanding how TSLP and other alarmin cytokines regulate immune response to ICB therapy at barrier sites will have major therapeutic implications." (PMID 37427591, 2023). "IAId could promote the interaction of activated AhR receptors with TSLP, thereby inhibit the production of TSLP, and ultimately reduce the occurrence of AD-like dermatitis." (PMID 38318507, 2023). "Interestingly, these upregulated cytokines can synergistically promote the production of TSLP by keratinocytes, suggesting the existence of a positive feedback loop that amplifies skin inflammation." (PMID 38053996, 2023). "Our study suggests that ghrelin may help to reduce skin inflammation through GR and PKCδ-p300-NF-κB-mediated suppression of TSLP gene activation." (PMID 35409338, 2022). "Altogether, these data indicate that IFN-γ-iMSC-EVs ameliorate skin inflammation by inhibiting the proliferation of immune cells and blocking TSLP expression, all of which might be involved in the reduced activity of the NF-κB pathway." (PMID 36496385, 2022). "Combined with the null role of r-Langerin+ dDCs in the inflammation, these results indicated that i-Langerin+ dDCs might facilitate the TSLP production in the early stage of MC903-induced AD-like dermatitis." (PMID 36304463, 2022). "Morphologically, we found TSLP expressed in each dermatosis to some extent." (PMID 36046760, 2022). "High levels of TSLP are found in lesional skin of patients with allergic forms of dermatitis." (PMID 34833113, 2021). "We could further show the up-regulation and activation of the AP-1 family of transcription factors during atopic-like skin inflammation and its involvement in TSLP production from the skin explant cultures." (PMID 34833113, 2021). "Due to aberrant skin microbiota, a reduced level of IAId may indicate alterations in TSLP expression, leading to skin inflammation in patients diagnosed with AD." (PMID 33499346, 2021).
dermatitis (continued). "Given the critical role of TSLP in inducing itching in pruritic skin disorders, TSLP may also be involved in BP itching." (PMID 34249003, 2021). "In skin inflammation, TSLP is important at the initial step and the late phase of inflammation." (PMID 33029540, 2020). "Delgocitinib was even found to be superior to conventional therapeutic agents like cyclosporine or tacrolimus ointment in hapten- and in TSLP-induced murine dermatitis models with respect to ear thickness, microscopic phenotype, inflammatory cytokine production, and serum IgE level." (PMID 31447854, 2019). "To investigate the induction of skin inflammation, we measured TSLP mRNA expression in the skin." (PMID 32038618, 2019). "Inhibition of Jak1 and Jak2 by topically applied ruxolitinib or momelotinib successfully decreased inflammation in a hapten-induced hypersensitivity model as well as in TSLP-induced dermatitis in mice together with the down-regulation of mRNA expression of IL-4, IL-5, IFNγ, and TSLP in the skin." (PMID 31447854, 2019). "Both spontaneous and allergen-induced dermatitis in Plcb3−/−mice required the receptor for TSLP." (PMID 26379670, 2015). "Another common pathway for skin inflammation might be overexpression of thymic stromal lymphopoietin (TSLP), an IL-7-like cytokine produced by keratinocytes, in lesional epidermis." (PMID 26379670, 2015). "As they are known to have an increased risk of developing hematopoietic malignancies correlating with the severity of their dermatitis, we analyzed serum from AD patients and found 2 out of 4 patients had increased TSLP levels (50 and 57 pg/ml compared to undetectable levels in all controls)." (PMID 20174635, 2010). "Though the mechanism of how skin exposure to allergen induces sensitization is not fully characterized and may even be allergen-specific, recent studies suggest that mechanical injury could promote skin inflammation and induce Thymic stromal lymphopoietin (TSLP) and Th2 cytokines." (PMID 40115160, 2024). "Indeed, SSA ameliorates AD-like skin inflammation by reducing EGR1-mediated TSLP expression in HaCaT keratinocytes; however, the effect of SSA on the expression of FLG remains unclear." (PMID 39274912, 2024). "However, while skin-associated ILC2 responses and AD-like dermatitis in a murine AD model are critically dependent on TSLP signaling, they are not dependent on IL-25 signaling." (PMID 38590314, 2024). "The available evidence strongly indicates that TSLP, IL-13 and IL-1ß are the key cytokines involved in the pathogenesis of AD, with these cytokines playing a substantial role in mediating various clinical manifestations of AD, including skin inflammation and pruritus." (PMID 38817611, 2024). "In this study, we found that Stat3 cKO mice exhibited worsened AD-like skin inflammation characterized by a defective skin barrier, Staphylococcus-dominant microbial dysbiosis, more infiltrating immune cells, and an increased concentration of keratinocyte-derived TSLP." (PMID 38053996, 2023). "In this study, Staphylococcus dominance and corresponding transcriptomic alterations in the skin were found in Stat3 cKO mice with AD-like skin inflammation, suggesting that Staphylococcus-dominant microbial colonization may be trigger TSLP expression in Stat3 cKO mice." (PMID 38053996, 2023). "Therefore, intradermal TSLP injection is often used to induce AD-like dermatitis in mice." (PMID 31447854, 2019). "The parallel improvements in ROS reduction, TSLP/ET‐1 suppression, and HAS upregulation suggest a multi‐targeted mode of action, which is especially valuable in treating multifactorial skin disorders." (PMID 41388848, 2025). "The deficiency of filaggrin increases the expression of keratinocyte-derived thymic stromal lymphopoietin (TSLP), which is crucial for the onset of skin inflammation in AD." (PMID 37374201, 2023).